SLC10A2 (solute carrier family 10 member 2)
Diseases named in the same sentence as SLC10A2 in open-access papers:
SLC10A2 is named in the same sentence as 72 diseases in open-access papers, as found by Europe PMC text mining. Sharing a sentence is not in itself a finding about the gene and the disease. The quoted sentences say what the papers report.
cholestasis (20 papers, 2009 to 2025). Impairment of the bile flow caused by obstruction within the liver, or outside the liver in the bile duct system. "The occurrence of gallstones as a potential adverse effect of the new class of SLC10A2 inhibitors, such as odevixibat to treat cholestasis or elobixibat to treat constipation, therefore deserves attention." (PMID 37277652, 2023). "Our study includes numerous such examples, supported by the recent launch of new drugs such as evinacumab, a monoclonal antibody targeting angiopoietin-like 3 (ANGPTL3) to treat dyslipidemia, or the SLC10A2 inhibitor odevixibat to treat cholestasis." (PMID 37277652, 2023).
gallstones (7 papers, 2009 to 2023). Solid crystalline precipitates in the biliary tract, usually formed in the gallbladder, resulting in the condition of cholelithiasis. "With the discovery of gallstone-associated variants in SLC10A2, we highlight a role of the intestinal compartment of the enterohepatic circulation of bile acids in gallstone disease susceptibility." (PMID 30504769, 2018). "Together these data indicate that the variants in SLC10A2 affect gallstone risk through impairment of the bile acid reabsorption function of ASBT." (PMID 30504769, 2018). "Further analyses in larger cohorts are required to finally assess the role of genetic variants in SLC10A2 in human gallstone development and lipid metabolism." (PMID 22093174, 2011). "In conclusion, we identified SLC10A2 as a novel intestinal common susceptibility factor for gallstones in humans." (PMID 19823678, 2009). "Most importantly, an association of the SNP rs9514089 with gallstone prevalence was observed in two distinct human Caucasian populations suggesting that a genetic variant of SLC10A2 confers an increased risk of gallstone formation." (PMID 19823678, 2009). "In the current study, we identified the polymorphism rs9514089 of SLC10A2 as the first intestinal bile acid related candidate for the development of gallstones." (PMID 19823678, 2009). "In this study the SLC10A2 gene was investigated to identify novel genetic variants and their association with gallstone formation." (PMID 19823678, 2009). "The aim of the present study was to systematically analyze the SLC10A2 gene for genetic variants and to investigate whether the variants are associated with the development of gallstones." (PMID 19823678, 2009). "Based on these findings we hypothesized that mutations of the SLC10A2 gene might result in gallstone formation by impairing the bile acid pool size." (PMID 19823678, 2009). "The mutation P290S (rs56398830) rendering SLC10A2 dysfunctional, which was identified initially in a patient diagnosed with Crohn's disease, was present at higher frequency in the control population (5.2%) compared to gallstone carriers (2.6%, p = 0.3534, OR = 0.6393)." (PMID 19823678, 2009). "To assess whether the association results for the GG variant of the SLC10A2 gene were affected by confounding risk factors for gallstones, we performed a multivariate analysis that included the rs9514089 variant and lithogenic risk factors such as age, gender, BMI and plasma cholesterol levels." (PMID 19823678, 2009). "A decreased expression of the ileal ASBT gene SLC10A2 develops the formation of gallstone, and Comprehensive statistical analysis provides strong evidence that allele of rs9514089 is a genetic determinant especially in male non-obese gallstone carriers." (PMID 25107305, 2014). "As one of these mechanisms, a decreased expression of the ileal apical sodium-dependent bile acid transporter gene SLC10A2 in gallstone carriers was described previously." (PMID 19823678, 2009). "Sequence analysis was performed of all six exonic and flanking regions as well as of 2,400 base pairs of the SLC10A2 promoter in a cohort of gallstone carriers and control subjects from Stuttgart, Germany." (PMID 19823678, 2009). "In the current study we follow up on our previous work that investigated a role of the apical sodium-dependent bile acid transporter (ASBT, gene name SLC10A2) in gallstone formation." (PMID 19823678, 2009).
Hepatic steatosis (6 papers, 2018 to 2025). Steatosis is a term used to denote lipid accumulation within hepatocytes. "Nevertheless, the reduction in hepatic steatosis and fibrosis in groups treated with P. niruri extract and metformin is associated with an effective reduction in the hepatic mRNA of PPARγ, SLC10A2, and Coll α1." (PMID 30096951, 2018). "The apical sodium-dependent bile acid transporter (ASBT, Slc10a2) is important in the enterohepatic cycling of bile acids and plays an important role in fatty liver diseases." (PMID 35565941, 2022). "Accordingly, the overexpression of PPARγ and SLC10A2 in the HFD group might be a vital reason for hepatic steatosis." (PMID 30096951, 2018).
colorectal cancer (5 papers, 2008 to 2025). A primary or metastatic malignant neoplasm that affects the colon or rectum. "S. gallolyticus is known to be a species associated with colorectal cancer, activating the Wnt signaling pathway and leading to downregulation of the BA transporter Slc10A2, resulting in accumulation of BAs39." (PMID 32377002, 2020). "Bile acids, especially secondary bile acids, can promote the development of colorectal cancer, and SLC10A2 can promote this process." (PMID 32600423, 2020). "Ten of these genes (WDR67, RFXAP, RP11-50D16.3, CAB39L, THSD1, SPRY2, TGDS, CLDN10, SLC10A2, CD33L3) have been reported changed in tumor tissues, while only 2 (RP11-50D16.3, SLC10A2) have been reported to appear changed in colorectal cancer." (PMID 20467480, 2010). "Hence, variation in the SLC10A2 gene appears to be associated with colorectal adenoma, but not with progression to colorectal carcinoma." (PMID 18644122, 2008).
Crohn disease (5 papers, 2009 to 2024). A gastrointestinal disorder characterized by chronic inflammation involving all layers of the intestinal wall, noncaseating granulomas affecting the intestinal wall and regional lymph nodes, and transmural fibrosis. "For the SLC10A2 gene only a few dysfunctional mutations were identified in single patients diagnosed with Crohn's disease, hypertriglyceridemia and/or in patients with different forms of bile acid malabsorption." (PMID 19823678, 2009). "The first human mutation rendering SLC10A2 dysfunctional was identified in a patient with Crohn's disease." (PMID 19823678, 2009). "Interestingly, the IBD-associated genes altered by NCT were not affected by HFD with the exception of Slc10a2, a bile acid transporter that is reduced in Crohn’s disease." (PMID 35385524, 2022).
Alzheimer disease (4 papers, 2020 to 2024). A progressive, neurodegenerative disease characterized by loss of function and death of nerve cells in several areas of the brain leading to loss of cognitive function such as memory and language. "A SNP in close vicinity to SLC10A2 is associated with late-onset Alzheimer’s disease (LOAD) in humans." (PMID 38136948, 2023). "In learning SCR, the genes closest to two of them modulate transcription (Mir7025 and Tead1), and the gene closest to the third SCR (Slc10a2) is related to Alzheimer’s disease." (PMID 32410960, 2020).
colon cancer (4 papers, 2020 to 2023). "Meanwhile, in vitro assays revealed that ESM1 and SLC10A2 exert opposing roles in colon cancer cell proliferation, validating the accuracy of the model." (PMID 33330631, 2020). "Furthermore, we attempted to validate the functional effects of ESM1 and SLC10A2 on colon cancer cells in vitro." (PMID 33330631, 2020). "SLC10A2 (ASBT/Apical sodium-dependent bile acid transporter) and SLC30A10 (Solute Carrier Family 30 Member 10) are also downregulated in colon cancer." (PMID 36293321, 2022).
diabetes (4 papers, 2012 to 2025). "Hence, targeting of Slc10a2 may be a promising strategy to treat hypertriglyceridemia and diabetes." (PMID 22662222, 2012).
hypertriglyceridemia (4 papers, 2009 to 2018). A laboratory test result indicating elevated triglyceride concentration in the blood. "And bioinformatics studies discovered that the expression of slc10a2 was increased in high-grade hypertriglyceridemia patients." (PMID 29642873, 2018). "Thus, our data do not support the claim that loss-of-function variants in SLC10A2 cause hypertriglyceridemia." (PMID 30504769, 2018).
inflammatory bowel disease (4 papers, 2018 to 2025). A spectrum of small and large bowel inflammatory diseases of unknown etiology. "Dysfunctions of FABP6 and SLC10A2 are mainly involved in hepatobiliary diseases, inflammatory bowel disease, metabolic diseases and intestinal tumors." (PMID 35283765, 2022).
colitis (3 papers, 2020 to 2024). Inflammation of the colon. "Dysfunction in bile acid transporter ASBT (SLC10A2) is associated with colorectal cancer advancement, particularly in pediatric cases, and SLC7A2 deficiency exacerbates colitis and increases the risk of colitis-associated colon tumorigenesis." (PMID 38534987, 2024).
dyslipidemia (3 papers, 2022 to 2026). "The apical sodium-dependent bile acid transporter (ASBT, encoded by SLC10A2) is the sole transporter responsible for bile acid absorption in the human intestinal tract and is a therapeutic target for dyslipidemia." (PMID 41581875, 2026).
lung carcinoma (3 papers, 2018 to 2022). "The enhanced expression of slc10a2 triggered the expression of PPARγ, which ultimately caused an increase in PTEN expression and decrease in mTOR expression, implying that bexarotene decreases lung cancer cell survival through the slc10a2/PPARγ/PTEN/mTOR signaling pathway." (PMID 35631448, 2022). "CLEC4M, SLC10A2 and FGF4 have been found to be involved in lung cancer progression and the regulation of treatment resistance." (PMID 33005178, 2020).
sclerosing cholangitis (3 papers, 2018 to 2023). A chronic, autoimmune inflammatory liver disorder characterized by narrowing and scarring of the lumen of the bile ducts. "Pharmacological inhibition of the ileal apical sodium-dependent bile acid transporter (ASBT/SLC10A2) followed by a decline in intestinal BA uptake was reported to ameliorate cholestatic liver and bile duct injury in a mouse model of sclerosing cholangitis." (PMID 36771465, 2023).
cholelithiasis (2 papers, 2009 to 2011). The presence of crystallized deposits forming in the gallbladder or biliary tree, primarily composed of cholesterol, bilirubin, and bile. "Recently, a single nucleotide polymorphism (SNP) rs9514089 in SLC10A2 (apical sodium-dependent bile acid transporter gene) has been identified as a susceptibility variant for cholelithiasis in humans." (PMID 22093174, 2011). "Recently, SLC10A2 was suggested as a novel susceptibility gene for cholelithiasis in humans." (PMID 22093174, 2011). "We have identified SLC10A2 as a novel susceptibility gene for cholelithiasis in humans." (PMID 19823678, 2009). "In the Sorbs a nominal association of the SLC10A2 genotype and cholelithiasis was observed in the non-obese subgroup, even though the SNP effect could only be detected in women." (PMID 22093174, 2011).
colorectal adenoma (2 papers, 2008 to 2013). An adenoma that arises from the colon or rectum. "The C to T polymorphism at codon 169 of the human SLC10A2 gene is associated with colorectal adenomas, indicating the role of bile acids in the etiology of this disease." (PMID 23374508, 2013). "Recently, an association of colorectal adenoma with two variants (c.507C>T;p.L169L and c.511G>T;p.A171S) of the ileal sodium dependent bile acid transporter gene (SLC10A2) has been reported." (PMID 18644122, 2008). "In line with this concept, a recent study found an association of a specific mutation (c.507C>T;p.L169L) in the SLC10A2 gene and colorectal adenoma development." (PMID 18644122, 2008).
COVID-19 (2 papers, 2021 to 2024). A disease caused by infection with severe acute respiratory syndrome coronavirus 2. "The AUC values for these genes in depression patients surpassed 0.8, and those in COVID-19 patients exceeded 0.7, with the exception of COL10A1, SPSB4, and SLC10A2, whose AUC values were less than 0.7." (PMID 39588145, 2024).
Hypercholesterolemia (2 papers, 2013 to 2025). An increased concentration of cholesterol in the blood. "The information on functionally critical residues will contribute to the design of prodrugs for efficient drug delivery and SLC10A2 inhibitors for treatment of hypercholesterolemia." (PMID 23374508, 2013). "This information will contribute to the design of bile acid-conjugated prodrugs for efficient drug delivery or SLC10A2 inhibitors for hypercholesterolemia treatment." (PMID 23374508, 2013).
amyloidosis (1 paper, 2023). A disorder characterized by the localized or diffuse accumulation of amyloid protein in various anatomic sites. "Two other putative candidate genes, namely SLC10A2 and ZDHHC13, have been reported to be associated with amyloidosis in humans and/or mice in previous studies." (PMID 38136948, 2023).
asthma (1 paper, 2017). "Three CpG sites were significantly associated (FDR < 0.05) with asthma at age 4: cg22971191 in SLC10A2 (solute carrier family 10 (sodium/bile acid cotransporter) member 2), cg18515031 in C10orf104 (chromosome 10 open reading frame 104) and cg05712073 in ZNF384 (Zinc Finger Protein 384)." (PMID 28056824, 2017).
atherosclerosis (1 paper, 2021). A disease characterized by the build-up of fatty material and calcium deposition in the arterial wall resulting in partial or complete occlusion of the arterial lumen. "A study in mice deficient in ileal apical sodium-dependent bile acid transporter (ASBT, SLC10A2) showed reduced intestine Fgf15 expression, higher hepatic Cyp7A1 expression and resistance to atherosclerosis development." (PMID 35116006, 2021).
breast carcinoma (1 paper, 2023). "The resulting formulation was resistant to acidic in vitro conditions mimicking those in the stomach, and the prodrug was able to enter MDA-MB-231 breast cancer cells, with uptake reduced by the addition of sodium taurocholate, indicating the involvement of ASBT/SLC10A2." (PMID 36770817, 2023).
colorectal polyps (1 paper, 2008). "Here, we reconstructed haplotypes of the SLC10A2 gene locus and tested for association with non-syndromic familial and sporadic CRC compared to 'hyper-normal' controls who displayed no colorectal polyps on screening colonoscopy." (PMID 18644122, 2008).
memory impairment (1 paper, 2023). "In this context, the solute carrier family 10 member 2 (SLC10A2) plays an important role in the regulation of cholesterol metabolism, and it has been shown that cholesterol accumulation in neurons leads to neuronal death, memory impairment, and increased Aβ generation." (PMID 36835161, 2023).
tumor (14 papers, 2005 to 2025). "As anticipated from these observations, using a traditional murine colon neoplasia model, compared to wild-type mice, we observed increased aberrant crypt foci and tumor formation in the colons of ASBT-deficient (Slc10a2-/-) mice." (PMID 29876009, 2018). "Five genes were subsequently selected by LASSO regression; CGB5, THPO, and PDGFRB were upregulated in the tumor tissue, while SLC10A2 and APOD were downregulated." (PMID 38228846, 2024). "Results showed that si-ESM1 inhibits the growth of tumor cells, while si-SLC10A2 promotes the proliferation of tumor cells." (PMID 33330631, 2020). "In recent years, animal experiments have also proven that a decreased transcriptional expression of SLC10A2 leads to an increase in fecal bile acids and stimulates tumor promotion." (PMID 33330631, 2020). "Downregulation of SLC10A2 could increase secretion of fecal bile acids and stimulate tumor promotion." (PMID 36890467, 2023). "We further explored whether slc10a2 via PPARγ plays an important role in tumor suppressor with the treatment of bexarotene." (PMID 29642873, 2018). "Besides the Na+ dependent ileal bile acid transporter (Slc10a2) and Slc34a2, the sodium transporter Slc5a8, a tumor suppressor gene, was also more highly expressed in the ileum compared to the jejunum, but similarly expressed in the colon." (PMID 15882471, 2005). "Similarly, SLC10A2 expression was also increased in normal tissues than in tumor tissues." (PMID 32788867, 2020).
metabolic disease (3 papers, 2021 to 2024). A congenital disorder (due to inherited enzyme abnormality) or acquired (due to failure of a metabolically important organ) disorder resulting from an abnormal metabolic process. "NTCP (SLC10A1) and ASBT (SLC10A2), as bile acid transporters, are indeed associated with the occurrence and development of metabolic diseases and may be potential therapeutic targets." (PMID 39850557, 2024).
infection (2 papers, 2016 to 2025). The state of being infected such as from the introduction of a foreign agent such as serum, vaccine, antigenic substance or organism. "Infection also down-regulated genes of the FXR pathway (e.g., NR1H4, FABP6, APOA1, SLC10A2), indicating disruption of the bile acid absorption in ileum." (PMID 26738723, 2016).
intestinal disorder (1 paper, 2024). A non-neoplastic or neoplastic disorder that affects the small or large intestine. "ASBT is an active sodium-dependent bile acid transporter (encoded by SLC10A2) responsible for ileal bile acid (BA) reabsorption and has also been linked to intestinal disorders like diarrhea." (PMID 39703373, 2024).
SLC10A2 also shares sentences with these, for which no sentence is quoted: Alagille syndrome (13 papers); Cholestatic liver disease (11); Pruritus (11); Obesity (10); familial intrahepatic cholestasis (6); cancer (5); Chronic constipation (4); progressive familial intrahepatic cholestasis (4); type 2 diabetes (4); hyperlipidemia (3); liver fibrosis (3); non-alcoholic steatohepatitis (3); primary biliary cholangitis (3); biliary atresia (2); Constipation (2); inflammation (2); intestinal tumor (2); liver disease (2); acute pancreatitis (1); adenocarcinoma (1); adenoma (1); alcoholism (1); Cholecystitis (1); cholesterol metabolism disorder (1); cognitive decline (1); colon adenocarcinoma (1); dementia (1); depression (1); Diarrhea (1); extrahepatic cholestasis (1).
A further 14 diseases each share a sentence with SLC10A2 in 1 paper.